LIN28B (lin-28 RNA binding posttranscriptional regulator B)
Diseases named in the same sentence as LIN28B in open-access papers (continued):
Sharing a sentence is not in itself a finding about the gene and the disease.
tumor (continued). "Lin28B does not significantly promote primary tumor growth but it can increase the ALDH+ BCSCs fraction." (PMID 35173168, 2022). "Using the MMTV-PyMT mouse model (luminal subtype), we showed that Lin28B has no influence on primary tumor growth, but promoted the occurrence of lung metastasis." (PMID 35173168, 2022). "Since both aberrantly expressed LIN28B and a high TGFBI tumour microenvironment are related to a more advanced disease stage among multiple tumour types, this interaction may also be important for LIN28B-positive CSC-like cells in other tissues." (PMID 34548635, 2022). "Indeed, both OTUD6B and LIN28B inactivation led to a significant reduction of MM tumor size, weight and volume and IHC analyses of the respective tumors showed an induction of apoptosis in both OTUD6B and LIN28B depleted tumors." (PMID 36059274, 2022). "In addition, the let-7 miRNA family, a group of well-known tumor-suppressing miRNAs, is a repressor of MYCN and can be repressed by LIN28B." (PMID 35008302, 2021). "Strong LIN28B expression was found mainly in tumor cells (in both the cytoplasm and the nucleus), but not in stromal cells." (PMID 30174831, 2018). "Lin28 and Lin28B each contain an N-terminal cold shock domain and a pair of retroviral-type CCHC zinc fingers near the C-terminus that confer RNA binding ability and inhibit the biogenesis of tumor-suppressive miRNAs of the let-7 family." (PMID 28947981, 2017). "Activation of LIN28B by C-MYC has also been confirmed in multiple human and mouse tumor models." (PMID 28400788, 2017). "Our results showed that Lin28A protein level is elevated with increase in tumor size, even though the difference between them is not significant, whereas the expression of Lin28B protein has not shown any difference between different tumor size stages." (PMID 27793004, 2016). "In order to confirm the role of LIN28B, PCAT5, and IGF2BP3 in tumor growth in vivo, we subcutaneously injected Ishikawa or HEC-1A cells with knockdown of LIN28B, PCAT5 and IGF2BP3 respectively, or a combined knockdown of LIN28B + PCAT5 + IGF2BP3 to construct a xenograft tumor model in nude mice." (PMID 38565547, 2024). "We cannot exclude that additional molecular mechanisms/pathways downstream to SOX6, independent from LIN28B downregulation concur to the observed tumor suppressive outcome and it is also likely that reduction of LIN28B expression does not exclusively impact the Let-7 axis." (PMID 38704454, 2024). "Finally, our in vivo study showed that knockdown of LIN28B, PCAT5, and IGF2BP3 could inhibit tumor growth in xenografted tumors, and mice injected with the combination of these three agents showed minimal xenografted tumor volume and weight." (PMID 38565547, 2024). "In addition, although Lin28b depletion in CAFs did not affect tumor desmoplasia, its expression is correlated with several cytokines secretion." (PMID 37898598, 2023). "Although previous studies mainly focused on the Lin28b’s function in tumors, the in vivo data from our study suggested that Lin28b could promote tumor growth in both cell-autonomous and non-cell-autonomous ways." (PMID 37898598, 2023). "However, the expressions of LIN28A and LIN28B are mutually exclusive, and tumor cells expressing LIN28A do not express LIN28B, and vice versa." (PMID 36831493, 2023). "Therefore, even without tumor cells arriving, Lin28B enables the pre-metastatic niche to produce IL-6 and IL-10, which is enough to induce N2 conversion." (PMID 35173168, 2022). "Prior to this, Lin28b and its role in tumor growth had not been adequately investigated." (PMID 31979130, 2020). "As LIN28AB expression is limited predominantly to tumor cells and conditional mouse knockout of either Lin28a or Lin28b at 6 weeks of age yields no overt phenotypes, it is anticipated that therapeutics targeting the LIN28/let-7 pathway will have minimal side effects in patients." (PMID 28400788, 2017).
tumor (continued). "RT-qPCR for Lin28B expression was further performed on 15 HCC tumor and non-tumor tissue pairs." (PMID 24244607, 2013). "Furthermore, LIN28B overexpression resulted in enhanced CDX2 expression to promote differentiation in subcutaneous xenograft tumors generated from CRC cells and metastatic tumor colonization through mesenchymal-epithelial transition in CRC liver metastasis mouse models." (PMID 33755595, 2021). "Note that the LIN28A/B expression levels were very low and did not correlate with the tumor purity (Spearman’s correlation coefficient r = 0.02 and −0.01, p = 0.7 and 0.85 for LIN28A and LIN28B, respectively)." (PMID 35008302, 2021). "Another recent study used tumor tissue samples and matched adjacent non-cancerous tissues as well as lymph node metastatic lesions from OSCC patients and measured Lin28B transcript levels via quantitative real-time polymerase chain reaction (qRT-PCR)." (PMID 32957697, 2020). "We also did not observe any positive correlation between LIN28A and LIN28B and MYC at the mRNA level in TCGA dataset or by IHC between LIN28A and MYC on our 80 GBM tumor tissue microarray." (PMID 23846349, 2013). "Notably, LIN28B overexpression renders AML cells growth independent of cytokines and enhances tumorigenicity in vivo, suggesting the role of LIN28B in more aggressive tumor phenotype." (PMID 28693523, 2017).
infection (4 papers, 2013 to 2023). The state of being infected such as from the introduction of a foreign agent such as serum, vaccine, antigenic substance or organism. "Neonatal CD8+ T cells exhibited higher glycolytic activity than adult CD8+ T cells after infection, which might be caused by age-related differences in lin-28 homolog B (Lin28b) expression." (PMID 37422501, 2023).
adenocarcinoma (3 papers, 2014 to 2023). A common cancer characterized by the presence of malignant glandular cells. "They discovered that both LIN28A and LIN28B expression promote tumor initiation, but LIN28B-induced tumors more frequently progressed to advanced adenocarcinomas in intestinal tissues and in a genetic mouse model." (PMID 37304235, 2023). "Vil-Lin28bMed mice express higher levels of Lin28b, have partially depleted Let-7 miRNAs and develop adenocarcinomas of the small intestine as do Lin28bLo/Let7IEC-KO mice but do not exhibit a phenotype as severe as Lin28bLo/Let7IEC-KO mice." (PMID 26244988, 2015).
hematological malignancies (3 papers, 2014 to 2017). "The RNA-binding protein, LIN28B, has been implicated in various solid tumors and hematological malignancies, including AML." (PMID 28693523, 2017). "Thus, LIN28B over-expression has been detected in several tumors and hematological malignancies, suggesting a role of this molecule in (promoting) invasiveness." (PMID 24498170, 2014).
colon (2 papers, 2013 to 2014). "It seems that Lin28B was more often expressed in the digestive system neoplasm, while Lin28A was expressed in germ cell development and gonadal tumours." (PMID 24386298, 2013). "We hypothesise that Wnt/APC-Myc pathway activation is the initiating event and that the LIN28B-let-7-c-Myc/LIN28B feedback loop accelerates colon carcinogenesis." (PMID 25360631, 2014).
hematopoietic cancers (1 paper, 2024). "Lin28B overexpression (OE) was also shown to play a role in a positive feedback loop connecting inflammatory response and hematopoietic cancer formation via the NF-κB-LIN28B-IL-6-STAT3 pathway." (PMID 39113694, 2024). "Whereas previous studies 28,42 have focused on the oncogenic implications of Lin28B-mediated inflammation in hematopoietic cancers, our research emphasizes the broader impact of Lin28A (and probably also Lin28B) dysregulation on inflammatory processes." (PMID 39113694, 2024).
LIN28B also shares sentences with these, for which no sentence is quoted: atypical teratoid rhabdoid tumor (2 papers); brain cancer (2); colorectal (2); endometrial cancer (2); germ cell tumor (2); head and neck cancer (2); metastatic disease (2); preeclampsia (2); acute lymphoblastic leukemia (1); alcoholic (1); bladder tumor (1); cervical cancer (1); colonic adenocarcinoma (1); deafness (1); diabetic nephropathy (1); embryonal tumors (1); gallbladder carcinoma (1); gastric adenocarcinoma (1); germ cell cancer (1); intestinal cancer (1); invasive carcinoma (1); liver cirrhosis (1); liver disease (1); liver steatosis (1); metabolic disorders (1); multiple sclerosis (1); ocular melanoma (1); pancreatic adenocarcinoma (1); pediatric cancers (1); pediatric kidney cancer (1).
A further 7 diseases each share a sentence with LIN28B in 1 paper.